PLA2G1B (phospholipase A2 group IB)
Description:
Secretory calcium-dependent phospholipase A2 that primarily targets dietary phospholipids in the intestinal tract. Hydrolyzes the ester bond of the fatty acyl group attached at sn-2 position of phospholipids (phospholipase A2 activity) with preference for phosphatidylethanolamines and phosphatidylglycerols over phosphatidylcholines. May play a role in the biosynthesis of N-acyl ethanolamines that regulate energy metabolism and inflammation in the intestinal tract. Hydrolyzes N-acyl phosphatidylethanolamines to N-acyl lysophosphatidylethanolamines, which are further cleaved by a lysophospholipase D to release N-acyl ethanolamines (By similarity). May act in an autocrine and paracrine manner. Upon binding to the PLA2R1 receptor can regulate podocyte survival and glomerular homeostasis. Has anti-helminth activity in a process regulated by gut microbiota. Upon helminth infection of intestinal epithelia, directly affects phosphatidylethanolamine contents in the membrane of helminth larvae, likely controlling an array of phospholipid-mediated cellular processes such as membrane fusion and cell division while providing for better immune recognition, ultimately reducing larvae integrity and infectivity (By similarity).
Synonyms: PLA2; PLA2A; PPLA2
Tractability: Small molecule: a high-quality ligand is known; it belongs to a druggable protein family. Antibody: UniProt places it where antibodies can reach, with high confidence; its Gene Ontology location is reachable by antibodies, with high confidence; UniProt predicts a signal peptide or a membrane-spanning region. PROTAC: a small molecule that binds it is known.
Target class: Enzyme; Hydrolase
Gene: Protein-coding gene on chromosome 12 (120,322,115 to 120,327,779, reverse strand). Ensembl gene ENSG00000170890.
Subcellular location: Secreted
Pathways (Reactome):
Metabolism: Acyl chain remodelling of PC; Acyl chain remodelling of PE; Acyl chain remodelling of PG; Acyl chain remodelling of PI; Acyl chain remodelling of PS; Synthesis of PA
Developmental Biology: Developmental Lineage of Pancreatic Acinar Cells
Gene Ontology:
Molecular function: calcium ion binding; phospholipase A2 activity; signaling receptor binding; bile acid binding; phospholipid binding
Biological process: antibacterial humoral response; antimicrobial humoral immune response mediated by antimicrobial peptide; defense response to Gram-positive bacterium; fatty acid biosynthetic process; innate immune response in mucosa; lipid catabolic process; phosphatidylcholine metabolic process; phosphatidylglycerol metabolic process; positive regulation of cell population proliferation; positive regulation of fibroblast proliferation; positive regulation of podocyte apoptotic process; actin filament organization; arachidonate secretion; cellular response to insulin stimulus; intracellular signal transduction; leukotriene biosynthetic process; neutrophil chemotaxis; neutrophil mediated immunity; positive regulation of calcium ion transport into cytosol; positive regulation of immune response; positive regulation of interleukin-8 production; positive regulation of MAPK cascade; positive regulation of protein secretion; positive regulation of transcription by RNA polymerase II; regulation of D-glucose import; and 2 more
Cellular component: cell surface; extracellular region
Genetic constraint (gnomAD): Loss-of-function variants: 12 observed, 14.23 expected, observed/expected ratio (o/e) 0.84, 90% interval 0.54 to 1.37. The upper end of that interval is the gene's LOEUF score, 1.37, which puts it in group 5 of 6, group 1 being the genes least tolerant of losing a copy. Missense variants: 189 observed, 197.9 expected, observed/expected ratio (o/e) 0.96, 90% interval 0.85 to 1.08. Synonymous variants: 81 observed, 79.01 expected, observed/expected ratio (o/e) 1.03, 90% interval 0.86 to 1.23.
Homologues: Orthologues: chimpanzee PLA2G1B (98% identical), macaque PLA2G1B (94% identical), dog PLA2G1B (84% identical), pig PLA2G1B (81% identical), mouse Pla2g1b (78% identical), rabbit PLA2G1B (76% identical), guinea pig PLA2G1B (72% identical), tropical clawed frog pla2g1b (62% identical), zebrafish pla2g1b (49% identical), rat Pla2g1b (49% identical), Caenorhabditis elegans C03H5.4 (33% identical), Caenorhabditis elegans C07E3.9 (33% identical). Paralogues in human: PLA2G2A (36% identical), PLA2G2E (34% identical), PLA2G2D (33% identical), PLA2G10 (31% identical), PLA2G5 (30% identical), OC90 (30% identical), PLA2G2F (30% identical), PLA2G2C (28% identical).
Diseases named in the same sentence as PLA2G1B in open-access papers:
PLA2G1B is named in the same sentence as 44 diseases in open-access papers, as found by Europe PMC text mining. Sharing a sentence is not in itself a finding about the gene and the disease. The quoted sentences say what the papers report.
Obesity (9 papers, 2011 to 2025). Accumulation of substantial excess body fat. "Conversely, pancreatic acinar cell-specific overexpression of Pla2g1b has been linked to increased phospholipid digestion and to exacerbation of diet-induced obesity and insulin resistance." (PMID 40225784, 2025). "In agreement, the PLA2G1B gene resides within a locus for obesity susceptibility in humans." (PMID 21673902, 2011). "Pla2g1b knock-out mice display reduced phospholipid digestion and concurrent attenuation of diet-induced obesity, insulin resistance, and atherosclerosis." (PMID 40225784, 2025). "PLA2G1B mediates lipid absorption, and PLA2G1B-derived metabolic products contribute to cardiometabolic diseases, including obesity, hyperinsulinaemia, and atherosclerosis." (PMID 36348490, 2022). "Inactivation of the group 1B PLA2 (PLA2G1B), a gut digestive enzyme, suppresses diet-induced obesity, hyperglycemia, insulin resistance, and hyperlipidemia in C57BL/6 mice and attenuates atherosclerosis and metabolic diseases in LDL receptor-deficient mice." (PMID 32957701, 2020). "PLA2G1B is a secreted group 1B phospholipase A2 that hydrolyzes membrane phospholipids and has been implicated in metabolic disorders (obesity/diabetes, hyperlipidemia, atherosclerosis), but it has not yet been linked to PD." (PMID 41373721, 2025). "PLA2G1B facilitates dietary fat absorption and can promote diet-induced obesity." (PMID 41514803, 2025). "Thus, perturbation of this process by gene disruption (Pla2g1b−/−) or pharmacological inhibition of sPLA2-IB led to protection from diet-induced obesity and insulin resistance due to decreased lipid digestion and absorption in the gut." (PMID 21673902, 2011).
Insulin resistance (4 papers, 2020 to 2025). Increased resistance towards insulin, that is, diminished effectiveness of insulin in reducing blood glucose levels. "Transgenic mice over-expressing the human PLA2G1B in pancreatic acinar cells gained more weight when given the hypercaloric high-fat/high-carb diet, and these mice also had reduced glucose tolerance and insulin resistance." (PMID 34512555, 2021).
Hyperglycemia (3 papers, 2016 to 2022). An increased concentration of glucose in the blood. "In rodent models, chemical inhibition and genetic inactivation of PLA2G1B are protective against the obesity and hyperglycemia induced by chronic feeding of a high-fat/high-carbohydrate diet 61,62." (PMID 35711841, 2022).
colitis (2 papers, 2023 to 2025). Inflammation of the colon. "PLA2G1B inactivation protects against DSS-induced colitis in mice by increasing the intestinal stem cell reservoir for epithelial repair and reducing myeloid cell inflammation in the diseased colon." (PMID 38003345, 2023).
lung adenocarcinoma (2 papers, 2020 to 2025). A carcinoma that arises from the lung and is characterized by the presence of malignant glandular epithelial cells. "Of these genes, PLA2G1B was reported to be associated with smoking-related lung adenocarcinoma, and UMODL1 may drive lung adenocarcinoma metastasis by involving the G-protein coupled receptor protein signaling pathway." (PMID 32484849, 2020). "Our expression analysis revealed that CDH3, EDNRB, MAOA, and PLA2G1B matched our differential gene analysis results in IPF, Lung Adenocarcinoma (LUAD), and Lung Squamous Cell Carcinoma (LUSC) tissues." (PMID 40589973, 2025).
lung carcinoma (2 papers, 2021 to 2025). "High expression of the PLA2G1B gene is related to increased susceptibility to lung cancer in mice and humans." (PMID 34434895, 2021). "Furthermore, our study investigated the relationship between IPF-ARGs and lung cancer, identifying CDH3 as an oncogenic gene and recognizing EDNRB, MAOA, and PLA2G1B as tumor suppressor genes." (PMID 40589973, 2025).
pancreatic cancer (2 papers, 2020 to 2022). "The highest score for differential expression and significant difference in genes associated with biological processes was the PLA2G1B (Phospholipase A2, group IB) gene, which was significantly down-regulated (9.26 times) in Mongolian pancreatic cancer tissue samples." (PMID 32272917, 2020). "Notably, high levels of arachidonic acid in plasma, which could be due to higher PLA2G1B/cofactor system activity, have been positively associated with the risk of pancreatic cancer." (PMID 35392090, 2022).
ulcerative colitis (2 papers, 2023 to 2025). An inflammatory bowel disease involving the mucosal surface of the large intestine and rectum. "Among them, PLA2G1B was involved in the progression of various diseases, including tumors, ulcerative colitis, and rheumatoid arthritis, etc." (PMID 41181152, 2025). "This study explored the influence of the abundantly expressed Group 1B PLA2 (PLA2G1B) on ulcerative colitis." (PMID 38003345, 2023).
Bovine mastitis (1 paper, 2018). INFLAMMATION of the UDDER in cows. "Following this and other indications that sPLA2s have primarily an anti-inflammatory role in the inflammatory response, we investigated the application of PLA2G1B as a therapeutic for bovine mastitis." (PMID 30148880, 2018). "This prompted us to investigate the therapeutic application of sPLA2, PLA2G1B, for bovine mastitis." (PMID 30148880, 2018). "Hence, this study strongly supports further research into PLA2G1B as a cure for bovine mastitis." (PMID 30148880, 2018).
gastric ulcer (1 paper, 2025). An ulcerated lesion in the mucosal surface of the stomach. "In a study of acetic acid-induced gastric ulcers in mice, PLA2G1B as one of the key target proteins regulated specific metabolites and was verified by PCR." (PMID 40964670, 2025).
infective endocarditis (1 paper, 2022). Infective endocarditis (IE) is an infection of the inner lining of the heart chambers (endocardium) and valves. "Staphylococcus aureus infections, such as superficial skin infections, infective endocarditis and sepsis could also be affected by the PLA2G1B/SA protein A cofactor pair." (PMID 35392090, 2022).
lung fibrosis (1 paper, 2023). "Interestingly, all these six dominant isoforms were found to be present only in structural cells like fibroblasts (PLA2G2A and PLA2G5), mesothelial cells (PLA2G2A) and epithelial cells (PLA2G1B, PLA2G3, PLA2G10 and PLA2G12A) that are key players in lung fibrosis." (PMID 37048117, 2023).
lymphopenia (1 paper, 2022). Reduction in the number of lymphocytes. "In a recent study, we demonstrated that the PLA2G1B/cofactor system is an inhibitor of CD4 T cells that is involved in the induction of anergy and lymphopenia of CD4 T cells in HIV-infected patients." (PMID 35392090, 2022). "Active PLA2G1B was initially described for its role in the intestinal absorption of lipids before our recent demonstration of its role in CD4 T-cell anergy and CD4 T-cell lymphopenia in HIV-infected patients." (PMID 35392090, 2022).
melanoma (1 paper, 2023). A malignant, usually aggressive tumor composed of atypical, neoplastic melanocytes. "To predict the prognosis of melanoma patients, we calculated the risk score of each patient based on the expression and corresponding lambda value of seven genes (PLA2G2D, FUT8, PLA2G4E, PLA2G5, PLA2G1B, B3GNT2, and ST3GAL5)." (PMID 37205993, 2023).
pancreatic ductal adenocarcinoma (1 paper, 2022). An infiltrating adenocarcinoma that arises from the epithelial cells of the pancreas. "We thus tested the plasma of patients with pancreatic ductal adenocarcinoma (PDAC) for the presence of inhibitory PLA2G1B activity that impairs the CD4 T-cell response to IL-7." (PMID 35392090, 2022). "Notably, the bacteria Porphyromonas gingivalis, which is associated with pancreatic ductal adenocarcinoma (PDAC), encodes such a cofactor protein and increased PLA2G1B activity in PDAC patient plasma inhibits the CD4 response to IL-7." (PMID 35392090, 2022).
phaeochromocytoma (1 paper, 2016). "However, some genes associated with steroid, organic hydroxy compound, and alcohol-related processes that were upregulated in ZG samples from phaeochromocytoma patients (eg, CYP11B2, CYP39A1, PLA2G1B, and SULT1E1), were not significantly upregulated in ZG samples from adrenals with an APA." (PMID 27777363, 2016).
pulmonary arterial hypertension (1 paper, 2023). Pulmonary arterial hypertension (PAH) is a group of diseases characterized by mean pulmonary artery pressure >20 mmHg and elevated pulmonary arterial resistance leading to right heart failure. "A genome RNA expression profiling study had shown upregulation of PLA2G12A in addition to PLA2G1B and PLA2G2D in patients with pulmonary arterial hypertension secondary to IPF." (PMID 37048117, 2023).
staphylococcus aureus infection (1 paper, 2022). An infectious process in which the bacteria Staphylococcus aureus is present. "We have thus extended the PLA2G1B/cofactor system to HCV and Staphylococcus aureus infections and additional pathologies where microbial proteins with 3S-like motifs also increase PLA2G1B enzymatic activity." (PMID 35392090, 2022).
viral infection (1 paper, 2021). "These pathways allowed the identification of PLA2G1B (phospholipase A2 group IB) and KITLG (KIT ligand) DEGs, and both were considered as strongly related to viral infection." (PMID 34696484, 2021).
tumor (6 papers, 2019 to 2025). "Some of them are considered as the tumor suppressor genes of PC, such as PLA2G1B, SERPINI2 and NR5A2." (PMID 31706267, 2019). "C4BPA and PLA2G1B showed the most positive (19.8) and negative (0.009) fold changes in gene expression, respectively, when comparing Group B1 differentially expressed mRNA in the post-chemotherapy tumor bed to Group A." (PMID 39249118, 2024).
cancer (3 papers, 2009 to 2022). A tumor composed of atypical neoplastic, often pleomorphic cells that invade other tissues. "Recent studies point to a relationship between PLA2G1B and PDE4C with cancer." (PMID 35379165, 2022).
infection (1 paper, 2022). The state of being infected such as from the introduction of a foreign agent such as serum, vaccine, antigenic substance or organism. "Several genes were significantly upregulated (Pla2g4a, Pla2g4c, Pla2g7, Ptgs1, Ptgs2, Pla1, Tbxas1) or downregulated (Alox5, Pla2g2d, Pla2g1b, Pla2g4b, Pla2g4f) during infection." (PMID 35812400, 2022).
inflammation (1 paper, 2020). Aberrant reaction of the microcirculation characterized by movement of fluid and leukocytes from the blood into extravascular tissues. "The protein encoded by the PLA2G1B gene is phospholipase A2, which plays a key role in membrane channel activation, information transmission, hemodynamics, and pathophysiology during pancreatic inflammation and after tissue injury." (PMID 32272917, 2020).
PLA2G1B also shares sentences with these, for which no sentence is quoted: atherosclerosis (4 papers); aortic stenosis (1); bipolar affective disorder (1); bladder cancer (1); central obesity (1); colorectal (1); Darier disease (1); diabetes (1); Giardia infection (1); glioblastoma (1); heart failure (1); hepatitis C virus infection (1); hyperlipidemia (1); infectious disease (1); Lung Squamous Cell Carcinoma (1); metabolic disease (1); pancreatitis (1); parasite infection (1); rectal cancer (1); rheumatoid arthritis (1); Sepsis (1).